GBP1 (guanylate binding protein 1)
Diseases named in the same sentence as GBP1 in open-access papers (continued):
Sharing a sentence is not in itself a finding about the gene and the disease.
bacterial meningitis (4 papers, 2010 to 2023). Inflammation of the membranes surrounding the brain and spinal cord due to a bacterial infection. "GBP-1 has been detected in the serum or cerebrospinal fluid during infectious and inflammatory diseases including bacterial meningitis, systemic lupus erythematosus, rheumatoid arthritis and systemic sclerosis." (PMID 37645250, 2023). "GBP1 is a key to the protective immunity against microbial and viral pathogens and it is increased in the cerebrospinal fluid of patients with bacterial meningitis." (PMID 20927331, 2010). "Finally, we showed that p47‐GBP‐1 represents the predominant form of secreted GBP‐1, both in cell culture supernatants and, in vivo, in the cerebrospinal fluid of patients with bacterial meningitis, indicating that it may represent the biologically active form of extracellular GBP‐1." (PMID 28272793, 2017).
rheumatoid arthritis (4 papers, 2018 to 2023). A chronic, systemic autoimmune disorder characterized by inflammation in the synovial membranes and articular surfaces. "Significant upregulated expression of GBP1 was found in inflammatory disease such as rheumatoid arthritis." (PMID 36741232, 2023). "Patients with rheumatic diseases like rheumatoid arthritis, systemic lupus erythematosus, and systemic sclerosis, which are characterized by a chronic inflammatory vessel activation, show reduced levels of GBP-1 in their peripheral blood." (PMID 29530068, 2018).
tuberculosis (4 papers, 2022 to 2026). A chronic, recurrent infection caused by the bacterium Mycobacterium tuberculosis. "Many interferon pathway-related genes, including STAT1,GBP1,GBP5, IFI44, IFIH1, FITM3, have been described in whole-blood transcriptome studies of tuberculosis." (PMID 36059536, 2022).
autoimmune disease (3 papers, 2018 to 2023). A disorder resulting from loss of function or tissue destruction of an organ or multiple organs, arising from humoral or cellular immune responses of the individual to their own tissue constituents. "In vivo, a strong expression of GBP-1 is associated with the presence of inflammation and was detected in inflamed tissues during autoimmune diseases or IBD, where it is mostly associated with blood vessels." (PMID 37645250, 2023). "In vivo, GBP1 is related to the existence of inflammation and has been adhere to in inflammatory bowel diseases (IBD), autoimmune diseases and cancers." (PMID 32269280, 2020).
breast tumors (3 papers, 2017 to 2022). "As a single gene, GBP-1 also does not contribute to RFS, OS, or DMSF in ER+, ER+/HER2−, or HER2+ breast tumors." (PMID 35681772, 2022).
colitis (3 papers, 2021 to 2024). Inflammation of the colon. "Similarly, GBP1 was identified as differentially expressed in colitis-susceptible mice and in colitis-resistant mice." (PMID 33429950, 2021). "Murine GBP-1/GBP-2b is also upregulated during experimental colitis." (PMID 37645250, 2023). "Specifically, ICI-colitis is enriched in mucosal Th1 effector cells that highly express IFNγ inducible genes such as STAT1, CD74, and GBP1/5 when compared to healthy controls and colitis-naïve patients." (PMID 39247203, 2024).
esophageal squamous cell carcinoma (3 papers, 2019 to 2023). Esophageal squamous cell carcinoma (ESCC) is a type of esophageal carcinoma (EC) that can affect any part of the esophagus, but is usually located in the upper or middle third. "Moreover, GBP1 has been associated with promoting lymph node metastasis in esophageal squamous cell carcinoma." (PMID 37796192, 2023). "The criteria of the Allred scoring system used for evaluating GBP1 expression in esophageal squamous cell carcinoma cells in our study." (PMID 31998647, 2019). "Assuming the following recognized entities: “Guanylate-binding protein 1” as a GENE, “lymph node metastasis” as a PHENOTYPE and “esophageal squamous cell carcinoma” as DISEASE." (PMID 34680062, 2021). "We have the information that the gene Guanylate-binding protein 1 (GBP1) has a role in squamous cell carcinoma; that this gene promotes a lymph node metastasis phenotype and that the lymph node metastasis can be a phenotype of the disease esophageal squamous cell carcinoma." (PMID 34680062, 2021).
Ewing sarcoma (3 papers, 2022 to 2023). A small round cell tumor that lacks morphologic, immunohistochemical, and electron microscopic evidence of neuroectodermal differentiation. "On the basis of these findings, future studies to determine the association of Ewing tumor GBP1 expression/expression patterns with patient outcome are warranted." (PMID 36187937, 2022). "Their study revealed that the loss of BARD1 increases Ewing sarcoma sensitivity to DNA damage, with Guanylate-binding protein 1 playing a role in the DNA damage response within Ewing sarcoma organoids." (PMID 37686615, 2023). "We were able to demonstrate that GBP1 expression contributes to the apoptotic response to DNA damage in Ewing sarcoma." (PMID 36187937, 2022). "We conclude that loss of BARD1 expression is only one of many possible factors contributing to GBP1 expression in Ewing sarcoma." (PMID 36187937, 2022). "We found that guanylate-binding protein 1 (GBP1) is significantly upregulated upon BARD1 downregulation and we subsequently demonstrate a role for GBP1 in DNA damage sensitivity in Ewing sarcoma." (PMID 36187937, 2022). "Additional Ewing tumors were also stained (Ewing tumor #2 and #3) for GBP1 and demonstrate no expression (middle) or intercellular heterogeneity in expression (right)." (PMID 36187937, 2022).
Hepatitis (3 papers, 2020 to 2024). Inflammation of the liver. "Upregulated ISGs (ISG20, IFI16, TAP2, GBP1, PSMB9) in the hepatitis phase were associated with T cell and macrophage infiltration and positively correlated with ALT levels." (PMID 39135698, 2024).
inflammatory bowel disease (3 papers, 2018 to 2025). A spectrum of small and large bowel inflammatory diseases of unknown etiology. "A study has revealed the protective role of GBP1 in inflammatory bowel disease (IBD)." (PMID 40362284, 2025).
liver cancer (3 papers, 2020 to 2024). An epithelial or non-epithelial malignant neoplasm that arises from the liver. "Moreover, in recent years, GBP1 has been reported to play a pivotal role in the occurrence and development of tumors, including liver cancer." (PMID 36034715, 2022).
lymphoma (3 papers, 2014 to 2022). A malignant (clonal) proliferation of B- lymphocytes or T- lymphocytes which involves the lymph nodes, bone marrow and/or extranodal sites. "GBP1, GBP3, GBP4, and GBP6 were beneficial for overall survival, indicating that GBPs are favorable prognosis markers for tested leukemia and lymphoma types." (PMID 34294680, 2021). "In addition, we have identified a panel of novel transcriptional targets including IFI27, IFI44, GBP1, CFLAR and ARHGAP18 for IRF4 in lymphomas." (PMID 25207815, 2014). "In this study, we revealed that GBP1–5 are significantly downregulated in AML, ALL, or CLL patients compared with the non-leukemic population, and elevated levels of GBP1, GBP3, GBP4, and GBP6 are associated with prolonged survival time in leukemia and lymphoma patients." (PMID 34294680, 2021).
Salmonella Infections (3 papers, 2020 to 2025). Infections with bacteria of the genus SALMONELLA. "GBP1-deficient cells were also unable to cleave and activate caspase-4 upon LPS transfection or Salmonella infection (p32 fragment)." (PMID 32581219, 2020). "To confirm the phenotype, we generated GBP1–/– HeLa cells by CRISPR-Cas9 genome targeting and found that GBP1-deficiency completely abrogated LDH release down to the background levels that were observed in naive cells after Salmonella infection or LPS transfection, without altering bacterial entry." (PMID 32581219, 2020). "It is tempting to speculate that the loss of GBP2 led to the expansion of GBP4 in M. Myotis and E. fuscus since, in humans, upon Salmonella infection, GBP1 requires GBP2 and GBP4 to recruit caspase-4 to the surface of the bacteria." (PMID 38357541, 2024). "A network analysis identified an interaction between the Toll-like receptor pathway and Salmonella infection via TLR4 and TLR2, the NOD-like receptor pathway and Salmonella infection via GBP1, and the TNF signaling pathway and Salmonella infection via IRF1." (PMID 40005871, 2025). "RNA interference-mediated silencing of GBPs expression revealed a consistent reduction of LDH release in cells lacking GBP1 both after Salmonella infection as well as LPS transfection." (PMID 32581219, 2020).
serous ovarian cancers (3 papers, 2020 to 2024). "Similarly, we report that the level of GBP1 mRNA expression detected by RNA-seq correlates with better 5-year overall survival in the TCGA cohort consisting of 373 EOC samples, which include cystic, mucinous, and serous ovarian cancers." (PMID 32093058, 2020).
chlamydia (2 papers, 2012 to 2020). "There are also reports suggesting that GBP1 is involved in host immune response against chlamydia and viruses including vesicular stomatitis virus, encephalomyocarditis virus and Hepatitis C Virus." (PMID 23186538, 2012).
dengue (2 papers, 2018 to 2021). "Only one gene family, the guanine binding protein (GBP1/2) genes were regulated in severe dengue and during mild rDEN2Δ30 infection." (PMID 34031380, 2021). "The guanylate-binding proteins (GBPs) are IFN inducible, and GBP1 has been shown to be upregulated with an inhibitory effect during dengue virus infection." (PMID 29147886, 2018).
endothelial dysfunction (2 papers, 2018 to 2021). In vascular diseases, endothelial dysfunction is a systemic pathological state of the endothelium (the inner lining of blood vessels) and can be broadly defined as an imbalance between vasodilating and vasoconstricting substances produced by (or acting on) the endothelium. "We additionally identified three genes (JAK2, GBP1, and TNFSF10) whose mRNA transcription suppression by Lp299v in PBMCs was inversely correlated with brachial FMD% suggesting a potential more direct role for these proteins in inflammation-induced endothelial dysfunction in humans." (PMID 33597583, 2021).
head and neck cancer (2 papers, 2019 to 2025). A primary or metastatic malignant neoplasm affecting the head and neck. "In ovarian and head-and-neck cancers, however, GBP1 has been consistently associated with disease progression and the development of treatment resistance." (PMID 32117203, 2019). "Guanylate-binding protein 1 (GBP1), an interferon-stimulated gene induced by interferon-gamma (IFN-γ), has been implicated in tumor progression and treatment resistance in various cancers, including ovarian and head and neck cancers." (PMID 40975978, 2025). "Indeed, GBP1 protein levels are negative prognostic indicators in ovarian and head-and-neck cancer patient samples and are implicated in the progression of lung, brain, and other cancers as well." (PMID 32117203, 2019).
herpesvirus infection (2 papers, 2022 to 2023). "Moreover, at the early stage of Kaposi’s sarcoma-associated herpesvirus infection, GBP1 was found upregulated via NF-κB pathway." (PMID 37784054, 2023).
intestinal inflammation (2 papers, 2017 to 2021). "In particular, high levels of IFN-γ and markers of IFN-γ-activated endothelium, such as ICAM1, VCAM1, MAdCAM, CXCL10, or guanylate-binding protein-1 (GBP-1), can be detected in the gut mucosa of mice during DSS-induced intestinal inflammation." (PMID 29051760, 2017).
Kaposi's sarcoma (2 papers, 2019 to 2022). A malignant neoplasm characterized by a vascular proliferation which usually contains blunt endothelial cells. "GBP-1 is also inversely correlated with endothelial cell proliferation in Kaposi sarcomas and inflammatory cytokine induced inflammation in vivo." (PMID 35681772, 2022). "It was later confirmed that not only IFNs, but also inflammatory cytokines could induce the expression of GBP1, and human GBP1 has been detected in vivo in inflamed tissues connected with various diseases such as cutaneous lupus erythematosus, psoriasis and Kaposi's sarcoma." (PMID 31998647, 2019).
leishmaniasis (2 papers, 2018 to 2024). Infectious disease that is transmitted through the bite of hematophagous female phlebotomine sand flies. "In this study, the ROC curve analysis of the GSE55664 dataset (early vs. late phase) identified two significant hub genes, GBP1 and CXCL10, highlighting their potential as biomarkers for early leishmaniasis diagnosis, consistent with previous studies." (PMID 39342024, 2024).
leukemia (2 papers, 2021 to 2022). A malignant (clonal) hematologic disorder, involving hematopoietic stem cells and characterized by the presence of primitive or atypical myeloid or lymphoid cells in the bone marrow and the blood. "For example, GBP1 expression is lower in patients with leukemia and yields a survival benefit for these patients." (PMID 35847946, 2022). "Furthermore, the underlying molecular mechanism of GBP1 and GBP2 as apoptosis inducers, their clinical implications in leukemia, and their efficacy as potential chemotherapeutic agents were investigated." (PMID 34294680, 2021). "Collectively, these results demonstrate that GBP1 and GBP2 induce the mitochondrial apoptotic death of leukemia cells." (PMID 34294680, 2021). "The comparable mRNA levels of most GBP genes, (GBP1–5), except for GBP6, were significantly downregulated in the three types of leukemia." (PMID 34294680, 2021).
meningitis (2 papers, 2017 to 2020). A disorder characterized by acute inflammation of the meninges of the brain and/or spinal cord. "The p47‐GBP‐1 protein fragment was detected after acetone precipitation in the samples of the meningitis patients with the highest amounts of total GBP‐1 determined by ELISA (red bars and right panel)." (PMID 28272793, 2017). "A subsequent study identified, together with full-length GBP1, a 47 kDa GBP1 form in the supernatants of IFN-γ-stimulated endothelial cells, and in CSF samples of patients with meningitis." (PMID 32093058, 2020).
mesothelioma (2 papers, 2016 to 2020). A usually malignant and aggressive neoplasm of the mesothelium which is often associated with exposure to asbestos. "In addition, a previous report indicated GBP1 as a component of mesothelioma exosomal signature." (PMID 32093058, 2020).
osteoporosis (2 papers, 2018 to 2023). A condition of reduced bone mass, with decreased cortical thickness and a decrease in the number and size of the trabeculae of cancellous bone (but normal chemical composition), resulting in increased fracture incidence. "Together with previous study, high expression of GBP1 in monocytes and MSCs may be associated with the risk to osteoporosis, and inhibition of GBP1 expression may prevent development of osteoporosis and facilitate MSC-based bone regeneration." (PMID 29348519, 2018). "Collectively, our findings indicate GBP1 inhibits osteogenic differentiation of MSCs, and inhibition of GBP1 expression may prevent development of osteoporosis and facilitate MSC-based bone regeneration." (PMID 29348519, 2018). "Previous studies have shown high expression of GBP1 in circulating monocytes of premenopausal subjects was correlated to extremely low peak bone mass, which is considered as an important determinant of osteoporosis." (PMID 29348519, 2018).
Peri-Implantitis (2 papers, 2024 to 2025). An inflammatory process with loss of supporting bone in the tissues surrounding functioning DENTAL IMPLANTS. "The aim was to evaluate the association between single-nucleotide polymorphisms (SNPs) in genes involved in inflammation and bone metabolism (BMP-4, BRINP3, CD14, FGF-3, FGF-10, GBP-1, IL-1α, IL-1β, IL-10, LTF, OPG, and RANKL) and peri-implantitis." (PMID 41373620, 2025). "GBP1 rs7911 and BRINP3 rs1935881 SNPs were found to be significantly more prevalent in patients with peri-implantitis." (PMID 41373620, 2025).
pulmonary TB (2 papers, 2022 to 2026). "The top performing single biomarkers for pulmonary TB versus controls were CALCOCO2, SAMD9L, GBP1, IFITM3, IFIT3 and SNX10." (PMID 35720382, 2022).
rectum adenocarcinoma (2 papers, 2022 to 2024). An adenocarcinoma arising from the rectum. "GBP1 expression was positively correlated with TMB of BRCA (p = 0.001), COAD (p < 0.001), LUAD (p = 0.004), LUSC (p = 0.012), rectum adenocarcinoma (READ) (p = 0.0058), STAD (p < 0.001), and THYM (p = 0.023)." (PMID 35222540, 2022).
schizophrenia (2 papers, 2007 to 2017). A major psychotic disorder characterized by abnormalities in the perception or expression of reality. "In particular, IFITM2, IFITM3, SERPINA3, and GBP1 showed increased mRNA levels in schizophrenia (p-values from qPCR ≤ 0.01)." (PMID 17822540, 2007). "Our results give additional support to the inflammatory hypothesis for schizophrenia and provide four biological markers for the disease likely to be directly involved in inflammatory processes, namely GBP1, SERPINA3, IFITM2, and IFITM3." (PMID 17822540, 2007). "The paralogous genes of GBP1, MT2A and APOL1, including GBP2, MT1G, MT1E, MT1F, MT1L and APOLD1, were also upregulated in the schizophrenia cases." (PMID 28809853, 2017). "As it has been suggested that schizophrenia may be the consequence of a vascular-inflammation, we studied the mRNA levels of SERPINA3, IFITM2, IFITM3, and GBP1 in a human endothelial cell line (TIME), before and after stimulation with TNF-α." (PMID 17822540, 2007). "Both these analyses confirmed that mRNA levels of SERPINA3, IFITM2, IFITM3 and GBP1 were increased in schizophrenia and were not simply the consequence of an infection immediately prior to death." (PMID 17822540, 2007).
tularemia (2 papers, 2019). Tularemia is an infection caused by the bacterium Francisella tularensis. "Tularemia vaccine induced higher guanylate binding protein (GBP) responses at Day 2, with upregulation of genes encoding for GBP1P1, GBP5, GBP1, and GBP4 compared to the other vaccines at Day 3 (blue bracket)." (PMID 31878161, 2019). "GBP1 enhancement also predicted a higher peak antibody response, suggesting that activation of these genes plays a role in the magnitude of the humoral immune responses after tularemia vaccination." (PMID 31878161, 2019). "Changes in gene expression, including upregulation of STAT1, GBP1, and IFIT2, predicted tularemia-specific antibody responses." (PMID 31878161, 2019).
uveal melanoma (2 papers, 2022 to 2023). A melanoma derived from melanocytes of the uveal tract. "High GBP1 expression was associated with poor OS prognosis for patients with KIRP (p = 0.0061), LGG (p < 0.001), thymoma (THYM) (p = 0.026), and uveal melanoma (UVM) (p = 0.0018), while high GBP1 expression conferred a better prognosis for patients with OV (p = 0.0038) and SKCM (p < 0.001)." (PMID 35222540, 2022).
Ascites (1 paper, 2020). Accumulation of fluid in the peritoneal cavity (between the layers of the peritoneum that lines the abdomen). "Nonetheless, preliminary analysis suggests that further studies to evaluate the prognostic value of GBP1 levels in ascites are warranted." (PMID 32093058, 2020).
astrocytoma (1 paper, 2021). "We found that the expressions of GBP1, 2, 3, 4 were significantly increased in astrocytoma vs oligodendroglioma, and GBP2, 3 were highly expressed in oligoastrocytoma vs oligodendroglioma." (PMID 34759950, 2021).
atherosclerosis (1 paper, 2018). A disease characterized by the build-up of fatty material and calcium deposition in the arterial wall resulting in partial or complete occlusion of the arterial lumen. "Coupled with evidence from our network-based prioritization, this suggests that other members of the GBP family with similar expression patterns to GBP3 and GBP6, including the top-prioritized GBP1, might also play a role in atherosclerosis mediated by hypercholesterolemia." (PMID 30303482, 2018).
bladder cancer (1 paper, 2022). "GBP1 was also identified as more highly expressed in circulating monocytes from healthy donors following BCG vaccination, as well as in patients with bladder cancer following BCG instillation." (PMID 35930640, 2022).